MTNR1B (melatonin receptor 1B)
Diseases named in the same sentence as MTNR1B in open-access papers (continued):
Sharing a sentence is not in itself a finding about the gene and the disease.
diabetes (continued). "A study with 26,576 individuals from Candidate-gene Association Resource (CARe), assessed the relationship of the MTNR1B rs10830963 G allele with the likelihood of healthy individuals developing glucose intolerance (prediabetes) and of those with intolerance progressing to diabetes." (PMID 40428319, 2025). "Among the studied melatonin receptor genes, MTNR1B MTNR1A, and RORA showed strong association with both diabetes and obesity." (PMID 40697662, 2025). "Further studies confirmed that variants of the melatonin receptor 1B gene (MTNR1B) and the prolactin receptor gene (PRLR) were identified as the genetic risk factors for the comorbidity of diabetes and depression." (PMID 39611132, 2024). "The current study found a significant inverse correlation between birth weight and obesity and diabetes genes, including MTNR1B, NTRK2, PCSK1, and PTEN (r= -0.221, -0.235, -0.246, and − 0.418, respectively)." (PMID 36997916, 2023). "MTNR1B gene is located on chromosome 11q21 and synthesis melatonin receptor 2 in which this gene is related to all diabetes types including diabetes mellitus, type 1 diabetes, and gestational diabetes." (PMID 36997916, 2023). "A significant inverse correlation between birth weight and obesity and diabetes genes, including MTNR1B, NTRK2, PCSK1, and PTEN genes (r= -0.221, -0.235, -0.246, and − 0.418, respectively)." (PMID 36997916, 2023). "Mainstream genetic research on glucose metabolism or diabetes has focused largely on MTNR1B, with its higher expression levels and stronger genetic susceptibility association." (PMID 36986139, 2023). "Two SNPs, rs10830962 and rs10830963 in the MTNR1B gene, were associated with high FBG (≥ 100 mg/dL or currently on diabetes medication)." (PMID 31910446, 2020). "In previous studies on the rs1387153 and rs10830963, researchers found strong associations between the two SNPs of MTNR1B and T2DM, and also with FPG levels, which is an important phenotype for diabetes." (PMID 21658282, 2011). "Interestingly, both MTNR1B and PCSK7 polymorphisms have been associated with increased risk of diabetes." (PMID 33503923, 2021). "Whether polymorphisms in MTNR1B contribute to the susceptibility of CAD, and whether they contribute to diabetes and CAD through a common pathway should be investigated in the future study." (PMID 21470412, 2011). "Finally, we evaluated the effects of MTNR1B variants on the melatonin-induced glucose regulation response in a recall-by-genotype study of individuals without diabetes." (PMID 40064676, 2025). "However, it is thought that a shift in circadian rhythm due to short sleep duration and early morning food intake increases the risk of diabetes, not MTNR1B gene variations." (PMID 37511203, 2023). "However, another study observed no interactive effects of MTNR1B rs10830963 and shift work on diabetes risk." (PMID 35411403, 2022). "Interestingly, one target (MTNR1B) has previously been repurposed for diabetes treatment." (PMID 25946000, 2015). "The MTNR1B rs10830963 associated effects on non-autoimmune diabetes mellitus (DM) traits are discussed as an example, more specifically the differences in the genetic effect sizes for T2DM development and GDM development/therapy." (PMID 32373162, 2020). "Since the effect size of this variant on sleep status is largely unknown, more studies with larger sample size may be required before the conclusion that sleep duration or quality has no impact on the association between MTNR1B rs10830963 and diabetes-related traits can be drawn." (PMID 20398260, 2010). "The associations of 23 SNPs located within 17 candidate genes (MTHFR, PPARγ, LPL, INSIG, TCF7L2, FTO, KCNJ11, JAZF1, CDKN2A/B, ADIPOQ, WFS1, CDKAL1, IGF2BP2, KCNQ1, MTNR1B, IRS1, ACE) with overweight and obesity, diabetes, metabolic phenotypes, and MetS were examined in both studies." (PMID 24959828, 2014).
gestational diabetes mellitus (23 papers, 2011 to 2026). "In another study of a Korean population, two loci were found to be associated with gestational diabetes, including rs10830962 in MTNR1B and rs7754840 in CDKAL1." (PMID 36553520, 2022). "The rs10830963 variant of the Melatonin Receptor 1B (MTNR1B) gene is associated with the development of gestational diabetes mellitus (GDM)." (PMID 30477160, 2018). "Interestingly, genetic polymorphisms have not been linked with sleep or circadian phenotypes; rather, variations of the MTNR1B gene are associated with type 2 and gestational diabetes and also adolescent idiopathic scoliosis." (PMID 37092428, 2023). "Additionally, several meta-analyses have proved an association between the MTNR1B rs10830963 variant and the development of gestational diabetes mellitus (GDM)." (PMID 35008896, 2021). "Likewise, the MTNR1B-rs10830963 polymorphism is strongly associated with the development of gestational diabetes mellitus." (PMID 33138317, 2020). "Rs10830963 and rs1387153 in MTNR1B were also significantly correlated with gestational diabetes mellitus (GDM), the common metabolic disorder during pregnancy." (PMID 36768893, 2023). "At present, most studies on MTNR1b are related to polycystic ovary syndrome and gestational diabetes mellitus, and few studies on mammals have been published." (PMID 37520005, 2023). "We do agree with the authors’ final conclusion that such a meta-analysis should eventually confirm that the MTNR1B rs10830963 G allele is significantly associated with increased risk of gestational diabetes mellitus (GDM) development in pregnant populations with Asian and European ancestry." (PMID 32022227, 2020). "This is likely true in other settings known to regulate these genes, such as the regulation of gestational diabetes in pregnancy by MTNR1B and applying time varying models in these unique biological settings will likely reveal additional novel mechanisms of environment dependent regulation." (PMID 39091879, 2024). "In addition, recent reports demonstrated that melatonin receptor 1B (MTNR1B) gene polymorphisms may influence insulin secretion and pancreatic glucose sensing, causing gestational diabetes mellitus (GDM)." (PMID 36552008, 2022). "Since T2DM and gestational diabetes mellitus (GDM) share similar characteristics, we suspected that the two genetic polymorphisms in MTNR1B may be associated with GDM, and conducted association studies between the polymorphisms and the disease." (PMID 21658282, 2011).
Obesity (20 papers, 2008 to 2025). Accumulation of substantial excess body fat. "Our data indicate that polymorphisms in the MTNR1B gene are associated with obesity traits in African Americans." (PMID 34020621, 2021). "Multiple linear regression models identified sixteen MTNR1B variants that showed a nominally significant association (FDR p value ≤ 0.05) with continuous obesity traits (BMI and waist circumference)." (PMID 34020621, 2021). "In conclusion, our study identified several MTNR1B variants associated with obesity in the Jackson Heart Study Population." (PMID 34020621, 2021). "In this study, we examined the associations of polymorphisms in MTNR1B with obesity traits in a sample of African Americans at JHS." (PMID 34020621, 2021). "The results showed that specific MTNR1B polymorphisms are associated with obesity in HT patients." (PMID 40332199, 2025). "Nevertheless, the MTNR1B gene polymorphisms could be considered as minor risk factors for obesity in HT patients." (PMID 40332199, 2025). "Furthermore, several MTNR1B variants, such as rs76371840, rs8192552, rs6177139, rs6483208, rs4388843, rs4601728, and rs12804291, are associated with obesity traits, and may also increase the risk of T2DM indirectly." (PMID 36974476, 2023). "Two abstracts subsequently indexed by PubMed also fully confirm the identification of MTNR1B as a phenotype for obesity." (PMID 23402646, 2013). "Later in the abstract the word “traits” is, however strongly indicating MTNR1B as a phenotype of obesity." (PMID 23402646, 2013). "The different genetic effects of MTNR1B on glycemic traits in overweight/obesity individuals." (PMID 36974476, 2023). "The measured InfoCodex CL for MTNR1B as a phenotype of obesity is 3.6%." (PMID 23402646, 2013). "The InfoCodex semantic engine could still correctly combine the MTNR1B-related information “increased prevalence of obesity” in PMID 20200315 with “traits” in PMID 19088850 to infer MTNR1B as a phenotype of obesity." (PMID 23402646, 2013). "This study focused on the MTNR1B gene polymorphisms and their associations with obesity, and we acknowledge the limitation of not including other gene variants that may also contribute to an increased BMI." (PMID 40332199, 2025). "In a two-year study, Leticia Goni and others found a significant interaction between the melatonin receptor 1B (MTNR1B) gene and dietary fat intake, affecting changes in obesity level, body composition and fat distribution." (PMID 34579752, 2021). "Although African Americans have a higher prevalence of obesity and the highest prevalence of short sleep duration and insomnia compared to other ethnicities, there are no documented studies on the influence of MTNR1B on adiposity or the effect of insomnia on this association." (PMID 34020621, 2021). "Thus, the lack of association between common genetic variation within MTNR1B and these measures of body adiposity, as observed in this study, prompts us to suggest that this gene plays, if at all, only a minor part in the development of obesity." (PMID 19088850, 2008). "A simple PubMed search would have thus failed to immediately identify MTNR1B as an obesity phenotype." (PMID 23402646, 2013). "In PubMed, a search for “MTNR1B” AND “obesity” returned 9 documents, of which two (PMID: 20200315, 19088850) matched the PubMed abstracts selected by InfoCodex to substantiate its identification of MTNR1B as an obesity phenotype." (PMID 23402646, 2013). "As a phenotype of obesity, MTNR1B should not be considered novel, but it can be used to substantiate the soundness of InfoCodex results extracted from PubMed and to illustrate the associative retrieval mechanism." (PMID 23402646, 2013).
Insulin resistance (14 papers, 2008 to 2025). Increased resistance towards insulin, that is, diminished effectiveness of insulin in reducing blood glucose levels. "In conclusion, our study provides evidence that the MTNR1B rs10830963 polymorphism is significantly associated with early markers of insulin resistance in young Brazilian adults." (PMID 40428319, 2025). "The associations between the MTNR1B rs724030 variant and islet function/insulin resistance in the IFG/IGT individuals stratified by WHR." (PMID 39886031, 2024). "The associations between the MTNR1B rs724030 variant and glycemic quantitative traits, islet function/insulin resistance, and serum lipid levels stratified by BMI." (PMID 39886031, 2024). "The associations between the MTNR1B rs724030 variant and islet function/insulin resistance in the NGT individuals stratified by WHR." (PMID 39886031, 2024). "Consistent with previous research, MTNR1B rs10830963 has been linked to impaired insulin secretion and altered glucose homeostasis, which can predispose individuals carrying the G allele to increased insulin resistance risk." (PMID 40428319, 2025). "The pregnant women of concurrent rising levels of melatonin and MTNR1B gene contribute to increased insulin resistance, which may be genetically predisposed to GDM." (PMID 36974476, 2023). "The rs10830963 variant is common and located within the single 11 kb intron of the MTNR1B gene, and the SNP has been associated with altered receptor expression or signaling efficiency, potentially leading to impaired β-cell function, reduced insulin secretion, and consequent insulin resistance." (PMID 40428319, 2025). "Moreover, genetic variants of melatonin receptor 1B (MTNR1B) might affect melatonin function and influence susceptibility to insulin resistance and diet-dependent weight loss." (PMID 35053018, 2021). "Curiously, a large-scale population-based study reported an inverse correlation of the risk allele of MTNR1B with the hepatic insulin resistance (IR) index in nondiabetic participants." (PMID 36974476, 2023). "The MTNR1B rs10830962 G allele also increased the risk of GDM, and in women homozygous for the rs10830962 G allele, physical activity decreased maternal fasting insulin and insulin resistance (according to the homeostatic model assessment of insulin resistance, HOMA-IR)." (PMID 36974476, 2023). "Further investigations are warranted to identify possible additional effects of this locus on insulin resistance, possibly via impact on SLC36A4, as well as insulin secretion through MTNR1B." (PMID 37291194, 2023). "Four of these loci, all not previously implicated in post-challenge insulin resistance, were significantly associated with IFC (N = 52,474; SLC2A4, PPP1R3B, C2CD4A and MTNR1B)." (PMID 37291194, 2023). "On the other hand, women without the risk alleles of MTNR1B and GCK still would have been prone to GDM development if they consumed high amounts of fat in the form of sausage, presumably due to increased insulin resistance." (PMID 29340108, 2017). "If impaired insulin production was the main reason for increased GDM risk among carriers of the risk alleles of MTNR1B and GCK, this may explain why carriers of the risk alleles did not benefit as much as non-carriers from insulin resistance reduction due to lower fat consumption." (PMID 29340108, 2017).
breast carcinoma (9 papers, 2013 to 2025). "Association between breast cancer and MTNR1B (rs10830963) polymorphism (Multivariate Logistic Regression adjusted for age and BMI)." (PMID 40736027, 2025). "This study examines the impact of PD1 (rs36084323) and MTNR1B (rs10830963) polymorphisms on breast cancer risk in 112 breast cancer patients and 124 healthy controls in the Bangladeshi population." (PMID 40736027, 2025). "The genotype and allele frequencies of MTNR1B (rs10830963) polymorphism were also assessed among breast cancer cases and controls." (PMID 40736027, 2025). "The dominant models for both genes (AG + GG vs. AA for PD1 and CG + GG vs. CC for MTNR1B) exhibited statistically significant associations, further indicating a potential genetic influence on breast cancer risk." (PMID 40736027, 2025). "Dominant models for both genes (AG + GG vs. AA for PD1 and CG + GG vs. CC for MTNR1B) showed statistically significant associations with breast cancer susceptibility." (PMID 40736027, 2025). "The PD1 GG genotype appears to have a protective effect, significantly reducing the risk of breast cancer, while the MTNR1B CG genotype also demonstrates a potential protective role." (PMID 40736027, 2025). "Meanwhile, the GG genotype of the MTNR1b (encoding melatonin receptor MT2) gene rs#10830963 polymorphism significantly elevated the risk of breast cancer by about 21 times more than the CC genotype (OR = 20.67; 95% CI = 4.77-99.33)." (PMID 28415828, 2017). "In the genes controlling melatonin biosynthesis (AANAT) or melatonin receptors (MTNR1A and MTNR1B), several SNPs were associated with increased risk of breast cancer." (PMID 23822714, 2013). "The present study provides compelling evidence that PD1 (rs36084323) and MTNR1B (rs10830963) polymorphisms may influence breast cancer susceptibility." (PMID 40736027, 2025). "Also, a study from the UK Biobank including 216,702 participants and resulting in 2367 incident breast cancer showed that an evening chronotype was associated with breast cancer risk in females who carry the rs10830963 G risk allele in melatonin receptor 1B." (PMID 39940387, 2025). "Conversely, various potential pathogenic mechanisms may elucidate the connection among MTNR1B rs10830963 and breast cancer." (PMID 40736027, 2025). "This study aimed to investigate associations between breast cancer risk and PD1 (rs36084323) and MTNR1B (rs10830963) polymorphisms." (PMID 40736027, 2025). "The tumor-suppressive role of MTNR1B has been studied in numerous tumors (β-catenin signaling), including prostate, lung, gastrointestinal, and breast cancers." (PMID 33371790, 2021). "The study found that the GG genotype of the PD1 polymorphism is associated with a protective effect, whereas specific genotypes of the MTNR1B gene, particularly the CG heterozygous genotype, may exert a protective effect against breast cancer." (PMID 40736027, 2025). "Also, the increased incidence of breast cancer associated with the melatonin pathway genes is thought to be due to melatonin binding to and activation of MT1 and MT2, the melatonin receptors encoded by the MTNR1A and MTNR1B genes, triggering anti-oncostatic actions in human breast cancer cells." (PMID 31358835, 2019). "Notably, the recessive model of PD1 (GG vs. AG + AA) exhibited a lower OR (0.2873) compared to the corresponding recessive model of MTNR1B (2.307), suggesting that PD1 GG may play a more crucial role in breast cancer prevention." (PMID 40736027, 2025).
Glucose intolerance (5 papers, 2012 to 2025). Glucose intolerance (GI) can be defined as dysglycemia that comprises both prediabetes and diabetes. "On the other hand, single-nucleotide polymorphisms (SNPs) of MTNR1B were reported to be associated with glucose intolerance, cardiovascular diseases, systemic lupus erythematosus, and rheumatoid arthritis." (PMID 28961261, 2017). "We further analyzed the genetic association of MTNR1B variants for the risk of plasma glucose intolerance between the NGT and the abnormal groups including GIGT/ABN & GDM." (PMID 22768333, 2012). "In summary, our data suggests that the genetic variants within MTNR1B gene are associated with gestational glucose levels and gestational glucose intolerance." (PMID 22768333, 2012). "The MTNR1B variant rs1447352 was observed to have less influence on glucose intolerance than the other variants in this study." (PMID 22768333, 2012). "One of the underlying mechanisms could be polymorphisms of the melatonin receptor (MTNR1B) that are associated with a higher risk of glucose intolerance in children and adolescents." (PMID 35140394, 2022). "MTNR1B has even been found to be a predictor for the transition from normoglycaemia to glucose intolerance." (PMID 35106618, 2022). "As MTNR1B SNPs have been linked to glucose intolerance, subjects without hyperglycemia (GD = 15, HT = 1, healthy controls = 60) and all subjects without excluding glucose intolerance were both analyzed in the MTNR1B association study." (PMID 28961261, 2017).
Hyperglycemia (5 papers, 2010 to 2023). An increased concentration of glucose in the blood. "The most investigated MTNR1B rs10830963 variant has been associated with a prolonged melatonin production that could facilitate the development of hyperglycemia under specific environmental conditions." (PMID 35008896, 2021). "Common variants of MTNR1B, G6PC2 and GCK are associated with elevated FPG and impaired insulin secretion, both individually and jointly, suggesting that these risk alleles may precipitate or perpetuate hyperglycemia in predisposed individuals." (PMID 20628598, 2010).
Impaired glucose tolerance (5 papers, 2012 to 2023). An abnormal resistance to glucose, i.e., a reduction in the ability to maintain glucose levels in the blood stream within normal limits following oral or intravenous administration of glucose. "For example, a randomized crossover study showed that a later dinner was associated with impaired glucose tolerance in a subset of MTNR1B (melatonin receptor 1B) risk allele carriers." (PMID 36034454, 2022). "Likewise, a rare variant of melatonin receptor 1b (MTNR1B) has been recently identified and is associated with impaired glucose tolerance and an increased risk of type 2 DM." (PMID 36902233, 2023). "To investigate how glucose metabolism was related to MTNR1B, we analyzed individuals with impaired glucose regulation (impaired glucose tolerance and/or impaired fasting glucose)." (PMID 23226241, 2012).